ERCC1 (ERCC excision repair 1, endonuclease non-catalytic subunit)
Diseases named in the same sentence as ERCC1 in open-access papers (continued):
Sharing a sentence is not in itself a finding about the gene and the disease.
anemia (8 papers, 2011 to 2024). A reduction in the number of red blood cells, the amount of hemoglobin, and/or the volume of packed red blood cells. "Goekkurts’ team noted that grade 3–4 anemia, leukopenia, and neutropenia were associated with polymorphisms within the ERCC1 gene in gastroesophageal adenocarcinoma." (PMID 39596349, 2024). "ERCC1 rs11615 present consistent results with increased risk of grade 3-4 neutropenia or anemia in four studies, and ERCC1 rs3212986 show decreased risk of grade 3-4 hematologic toxicity in two studies." (PMID 39234108, 2024). "ERCC1 polymorphisms were also responsible for elevated risk of FAC-induced overall anemia (p.Asn118=) and recurrent neutropenia (c.1510C>A)." (PMID 29507678, 2018). "In particular, rs1128503 (ABCB1, C > T), rs12762549 (ABCC2, C > G), rs363717 (ABCA1, A > G) and rs11615 (ERCC1, T > C) were significantly associated with grade 3–4 anemia (p = 0.035, OR 1.58; p = 0.005, OR 0.55; p = 0.001, OR 1.31 and p = 0.024, OR = 1.58)." (PMID 25881102, 2015). "ERCC1 polymorphism were associated with platinum resistance, while GSTP1 polymorphism was associated with grade 2 of anemia." (PMID 32711417, 2020). "Because in our group triple negativity was the anemia predictor together with variant in NER’s component ERCC1, one could cautiously hypothesize, that the reduced ERCC1 expression in TNBCs is to some extent reflected in the expression on the patients’ level." (PMID 29507678, 2018). "Nor was there an association between ERCC1 19442C>A genotypes and grade 3 or 4 haematological toxicity during the first cycle (leukopenia, P=0.273; neutropenia, P=0.290; anaemia, P=1.000; thrombocytopenia, P=1.000)." (PMID 21364592, 2011). "The same was true for ERCC1 8525C>T (leukopenia, P=1.000; neutropenia, P=0.909; anaemia, P=0.310; thrombocytopenia, P=0.625), and for XRCC1 variation (leukopenia, P=0.672; neutropenia, P=0.600; anaemia, P=0.158; thrombocytopenia, P=0.590)." (PMID 21364592, 2011).
pancreatic cancer (8 papers, 2012 to 2023). "The results show that there was loss expression of MGMT, ERCC1, hMSH2, and hMLH1 in the course of genesis of pancreatic cancer induced by DMBA in rats, which might be the mechanism of carcinogenesis by DMBA." (PMID 24502441, 2014). "Some researchers found that patients with the ERCC1 118 T/T genotype were more likely to respond to oxaliplatin-based chemotherapy than carriers of the other genotypes in colorectal and pancreatic cancer." (PMID 23020798, 2012). "Therefore, the prognostic or predictive role of ERCC1 in pancreatic cancer is still unclear and the present analysis is to our knowledge the first study in a cohort of patients with mPC treated in first-line with the same oxaliplatin containing regimen." (PMID 27147577, 2016). "The DNA-repair proteins, including MGMT, ERCC1, hMSH2, and hMLH1, might play an important role in the genesis of pancreatic cancer induced by DMBA in rats." (PMID 24502441, 2014). "Therefore, testing the expression of MGMT, ERCC1, hMSH2, and hMLH1 in pancreatic cancer might play an important role in guiding the treatment of human pancreatic cancer." (PMID 24502441, 2014). "The expression levels of MGMT, ERCC1, hMSH2, and hMLH1 in pancreatic cancer and non-cancerous pancreatic tissues was detected and their effect on the process of inducing cancer by DMBA was assessed." (PMID 24502441, 2014). "RRM1 and ERCC1 expression does not seem to have a clear predictive or prognostic value in pancreatic cancer." (PMID 22436573, 2012).
small cell lung carcinoma (8 papers, 2010 to 2024). Small cell lung cancer (SCLC) is a highly aggressive malignant neoplasm, accounting for 10-15% of lung cancer cases, characterized byrapid growth, and early metastasis. "Summary of studies reporting ERCC1 expression and outcomes in non-small cell and small-cell lung cancer patients." (PMID 22022380, 2011).
XFE progeroid syndrome (8 papers, 2010 to 2025). A syndrome characterized by aged bird-like facies, lack of subcutaneous fat, dwarfism, cachexia and microcephaly. "In humans, deficiency of ERCC1 or XPF results in various conditions including xeroderma pigmentosum, Cockayne syndrome, cerebro‐oculo‐facio‐skeletal syndrome, Fanconi anemia, and XFE progeroid syndrome." (PMID 39604117, 2025). "Collectively, these data demonstrate that our model recapitulates the major phenotypes of both human XFE progeroid syndrome and previously generated Ercc1−/− models." (PMID 38514641, 2024). "The Ercc1−/− and Ercc1-/Δ7 mouse models of the human progeroid syndrome XFE provide compelling evidence that the persistent activation of DNA damage-driven innate immune responses lead to tissue-degenerative alterations." (PMID 36160606, 2022). "XFE progeroid syndrome, a disease of accelerated aging caused by deficiency in the DNA repair endonuclease XPF-ERCC1, is modeled by Ercc1 knockout and hypomorphic mice." (PMID 23852002, 2013). "Murine models of XFE progeroid syndrome (Ercc1−/− knock-out and Ercc1−/Δ hypomorphic mice) are well-characterized models that mimic the histopathology of normal aging." (PMID 23852002, 2013). "Total cellular XPF and ERCC1 are dramatically reduced in cells from a patient with XFE progeroid syndrome." (PMID 20221251, 2010). "Interestingly, in the same Ercc1 mutant mice, which model XFE progeroid syndrome, senescent cells accumulate in the same organs as occurs with normal aging in mice and to roughly the same extent." (PMID 33512317, 2021). "Moreover, ERCC4 mutations, encoding one of the catalytic subunits of ERCC1-XPF, cause XFE progeroid syndrome and Fanconi anemia, whose patients represent the symptoms of premature aging." (PMID 32526825, 2020).
hepatocellular carcinoma (7 papers, 2012 to 2025). A malignant tumor that arises from hepatocytes. "We define ERCC1-hepatorenal syndrome as a severe, multisystem DNA repair disorder associated with high morbidity and mortality, including a significant risk of pediatric hepatocellular carcinoma." (PMID 40684071, 2025). "ERCC1 polymorphism rs1046282 CC, identified in our study as a risk factor for early neutropenia, has been shown in the literature to have a more than two-fold lower risk of hepatocellular carcinoma." (PMID 39596349, 2024). "We now confirm this gene-disease association in a cohort of seven individuals with ERCC1-hepatorenal syndrome and expand the phenotype to include multi-organ failure and malignancy risk, particularly childhood-onset hepatocellular carcinoma (HCC)." (PMID 40684071, 2025). "The PFKFB3/AKT/ERCC1 (Excision repair cross-complementation group 1) pathway has been reported to promote the progression of hepatocellular carcinoma by enhancing DNA repair in the process of glycolysis." (PMID 36973739, 2023). "A study in hepatocellular carcinoma (HCC) patients showed that the level of ERCC1 in the cancer tissues was significantly lower than that in adjacent paracancer tissues and that the expression of ERCC1 was negatively associated with hepatic capsular and microvascular invasion." (PMID 33029487, 2020). "The current study aimed to investigate the expression levels of c-erb-B2, EGFR, PTEN, mTOR, PI3K, p27, and ERCC1 in hepatocellular carcinoma (HCC) and their correlation with other clinicopathologic features." (PMID 23162604, 2012). "With regard to the DNA repair system, it has been shown that specific MERK/ERK and PI3K inhibitors prevent ERCC1 induction, whereas JNK and p38 inhibitors are without effects in human hepatoma cells." (PMID 23299493, 2013).
lymph node metastasis (7 papers, 2012 to 2022). "The association of ERCC1 status with clinicopathological characteristics (age, histological grade, tumor size, parametrial invasion, lymph node metastasis and FIGO stage) and treatment response were analyzed." (PMID 23259415, 2012). "ERCC1 and ER expression, tumor size, blood vessel invasion, pathological type, and lymph node metastases significantly correlated (P < 0.05) with overall survival in patients." (PMID 36338712, 2022). "In high-risk group, such as lymph node metastasis or large tumor size, the gap in DFS became wider with higher protein expression, especially HER2 and ERCC1." (PMID 34350111, 2021). "However, a significant correlation (P < 0.05) was observed between ERCC1 expression, vascular tumor thrombus, pathological type, ER, tumor size, chemotherapy, lymph node metastasis, and OS." (PMID 36338712, 2022).
Cockayne syndrome (6 papers, 2008 to 2023). A multisystem condition characterized by short stature, a characteristic facial appearance, premature aging, photosensitivity, progressive neurological dysfunction, and intellectual deficit. "In addition, ERCC1 or ERCC4 mutation also have been reported in Cockayne Syndrome." (PMID 34440306, 2021). "Functionally relevant interactions with TRF2 at low incidence have been reported for other TRF2 interaction partners, including Mre11/Rad50/Nbs1, XPF/ERCC1 and Cockayne syndrome group B protein." (PMID 26799419, 2016). "Prime examples are Cockayne syndrome (CS; affected proteins: CSB, CSA), XPF-ERCC1 syndrome (XFE; affected proteins: XPF, ERCC1) or trichothiodystrophy (TTD; affected proteins: XPB, XPD, TTDA) that are caused by defects in the transcription-coupled subpathway of nucleotide excision repair (TC-NER)." (PMID 18704162, 2008).
kidney failure (6 papers, 2013 to 2025). An acute or chronic condition that is characterized by the inability of the kidneys to adequately filter the blood. "Data from whole-body Ercc1-null mice with correction of the liver phenotype also indicate a role for glomerular health, with Ercc1-deficient animals rapidly dying of renal failure." (PMID 40392611, 2025). "A child with mutations in XPF/ERCC1 displayed a unique combination of progeroid symptoms and died from kidney failure at the age of 16 years." (PMID 23947592, 2013). "Notably, liver-specific restoration of Ercc1 in deficient mice improved liver function and extended lifespan, but these mice later died of renal failure, with polyploidy observed in kidney tubule cells." (PMID 40684071, 2025). "To exclude the possibility that the more severe HSC defect in Ercc1-/- mice was being compounded by liver and kidney failure, we next quantified HSCs in embryos." (PMID 32271760, 2020).
nasopharyngeal carcinoma (6 papers, 2013 to 2024). A carcinoma arising from the nasopharyngeal epithelium. "ERCC1 gene polymorphisms have been associated with an increased risk of certain cancers, including nasopharyngeal carcinoma, lung cancer, melanoma, and pancreatic cancer." (PMID 38398017, 2024). "Increased expressions of ERCC1 and related polymorphisms are associated with decreased progression-free survival, increased susceptibility to nasopharyngeal carcinoma, increased rates of recurrence in patients treated with concurrent chemoradiotherapy, and increased resistance to radiotherapy." (PMID 38398017, 2024). "Combined Ki67 and ERCC1 can better predict nasopharyngeal carcinoma prognosis than individual parameters." (PMID 29179456, 2017). "This study aimed to assess the predictive value of combined Ki67 and ERCC1 in distant metastasis-free nasopharyngeal carcinoma." (PMID 29179456, 2017). "In conclusion, in nasopharyngeal carcinoma patients, ERCC1 and BRCA1 may be a predictor of response to platinum-based chemotherapy and concurrent radiochemotherapy." (PMID 28404895, 2017). "In this study, we examined ERCC1 and BRCA1 expression and clinical outcome of 201 phase-III-IV nasopharyngeal carcinoma patients who were treated with cisplatin-based induced chemotherapy and concurrent radiochemotherapy." (PMID 28404895, 2017). "The present study was designed to evaluate the utility of the XRCC1 Arg399Gln and ERCC1 Cys8092Ala SNPs, measured in pretreatment biopsy samples, as predictors of response to radiotherapy in patients with non-metastatic nasopharyngeal carcinoma (NPC)." (PMID 25025378, 2014).
neutropenia (6 papers, 2011 to 2025). A decrease in the number of neutrophils found in the blood. "Patients with the A/A genotype in rs11615 of the ERCC1 gene had significantly higher risk of neutropenia (P = .0133)." (PMID 31797573, 2020). "Patients harboring homozygous A/A genotype in rs11615 of ERCC1 showed significantly higher risk of neutropenia (any grade) during chemotherapy than heterozygous patients A/G (P = .0133; χ2 = 6.12)." (PMID 31797573, 2020). "However, the strongest factor for the recurrent neutropenia was the rare homozygote AA of the ERCC1 c.1510C>A polymorphism (rs3212986), responsible for the over 5-times higher risk when compared to genotypes with common allele C (OR 5.45; 95% CI 1.62–18.29; p = 0.006)." (PMID 29507678, 2018). "From the other hand, altered doxorubicin intake by the SLC22A16 variant (p.Asn104=) together with impaired drugs elimination (CYP2C19 p.Pro227=) and slower DNA damage repair with hematopoiesis disturbances (ERCC1 c.1510C>A) seemed to be the basis of recurrent neutropenia." (PMID 29507678, 2018).
brain tumors (5 papers, 2014 to 2024). "The result of association between the A allele of ERCC1 rs3212986 and increased risk of PBTs is in line with our finding in a meta-analysis of this polymorphism in adult brain tumors." (PMID 27613841, 2016). "Future studies may address the effect of the ERCC1 rs3212986 and ERCC2 rs13181 polymorphism on different histological brain tumor subtypes to provide a better understanding of tumor pathogenesis." (PMID 25674148, 2014).
COFS syndrome (5 papers, 2017 to 2025). Cerebrooculofacioskeletal (COFS) syndrome is a rare genetic disorder, belonging to a family of diseases of DNA repair, characterized by a severe sensorineural involvement. "At the moment, four different genes are known to cause COFS syndrome: ERCC6 (COFS1, MIM #214150), ERCC2 (COFS2, MIM #610756), ERCC5 (COFS3, MIM #616570), and ERCC1 (COFS4, MIM #610758)." (PMID 33766032, 2021). "Patients with Cockayne and COFS syndromes develop postnatal brain growth failure and degeneration of multiple tissues, resulting in cachexia, dementia and premature aging, as well as a shortened lifespan as observed in Ercc1−/Δ mice." (PMID 31737985, 2020). "In humans, ERCC1 mutations at residues 158 and 231, yielding a premature Q158X termination mutation, and a F231L mutation in the XPF‐interacting domain have been reported to cause Cockayne and COFS syndromes." (PMID 31737985, 2020).
esophageal squamous cell carcinoma (5 papers, 2014 to 2018). Esophageal squamous cell carcinoma (ESCC) is a type of esophageal carcinoma (EC) that can affect any part of the esophagus, but is usually located in the upper or middle third. "Few studies have targeted tumor cell-specific expression of ERCC1 as a potential correlate for the progression of squamous cell carcinoma of the esophagus, and our findings yield interesting potential associations between ERCC1 SNP C8092A and survival of patients with this disease." (PMID 25191856, 2014). "The present study aimed to investigate the relationship between ERCC1 SNP and prognostic indication, histological and clinical outcomes in patients undergoing treatment for squamous cell esophageal carcinoma." (PMID 25191856, 2014). "In human esophageal SCC, the protein expression of p16, RAR-β2, and TIMP3 is decreased, and ERCC1 and BRCA1 protein expression varies." (PMID 27410681, 2016). "Combined treatment of chemotherapy and radiation is considered one of the most useful therapeutic paradigms for esophageal squamous cell carcinoma (ESCC), which potentiates a connection between genetic factors like ERCC1 SNP and individual treatment outcome." (PMID 25191856, 2014). "However, to the best of our knowledge no study has been conducted using ERCC1, TYMS, TUBB3, RRM1 and TOP2A simultaneously in esophageal squamous cell carcinoma (ESCC)." (PMID 24926347, 2014).
hepatorenal syndrome (5 papers, 2024 to 2025). Hepatorenal syndrome is a form of impaired kidney function that occurs in individuals with advanced chronic liver disease. "In conclusion, we describe a cohort with ERCC1-hepatorenal syndrome, characterized by progressive cholestatic liver disease, early-onset HCC, renal impairment, photosensitivity, and growth restriction." (PMID 40684071, 2025). "Mouse models thus recapitulate key features of ERCC1-hepatorenal syndrome, although early-onset HCC and end-stage renal disease remain unique to humans, possibly due to species-specific or environmental factors." (PMID 40684071, 2025). "The liver phenotype in individuals with ERCC1-hepatorenal syndrome closely mirrors these models, including accelerated liver aging, hepatocellular senescence, fibrosis, increased polyploidy, apoptosis, and reduced regenerative capacity." (PMID 40684071, 2025). "In ERCC1-hepatorenal syndrome, chemotherapy must be used cautiously due to increased toxicity from DNA repair defects." (PMID 40684071, 2025). "Secondly, Ercc1−/− mice develop renal insufficiency with elevated blood serum levels of urea and proteinuria." (PMID 38514641, 2024). "These manifestations reveal a new ERCC1-hepatorenal syndrome." (PMID 40684071, 2025). "Given the age-dependent nature of the phenotype, it is plausible that this individual could be affected by ERCC1-hepatorenal syndrome but included in the database due to young age at phenotyping." (PMID 40684071, 2025). "This study provides a detailed characterization of the ERCC1-hepatorenal syndrome phenotype." (PMID 40684071, 2025). "For example, Xpa/Fanca double-KO mice, deficient in both NER and ICL repair, do not develop liver disease, suggesting other ERCC1-dependent pathways may offer protection." (PMID 40684071, 2025). "This suggests that kidney dysfunction is not secondary to liver disease but reflects a direct, cell-intrinsic role for ERCC1 in renal protection." (PMID 40684071, 2025).
leukopenia (5 papers, 2011 to 2024). "The multivariate analyses showed an association between specific ERCC1/2 genotypes and cumulative dose of BEP drugs with the appearance of severe leukopenia and/or febrile neutropenia." (PMID 30914949, 2019). "Multivariate analysis showed an association between specific ERCC1/2 genotypes and cumulative dose of BEP drugs with the appearance of severe leukopenia and/or febrile neutropenia." (PMID 30914949, 2019). "However, we could not find any association between ERCC1-rs11615 and haematological toxicity, as was shown in a Chinese population with non-small lung cancer for the ERCC1-rs11615 genotype T/T to be correlated with severe leukopenia." (PMID 32397974, 2020).
rectal cancer (5 papers, 2013 to 2024). A primary or metastatic malignant neoplasm that affects the rectum. "We evaluated the association of the ERCC1 level with/without radiation exposure between the markers of MET and EMT in rectal cancer cells." (PMID 36230725, 2022). "Initially, we considered that the overexpression of ERCC1 would only affect staged outcomes of chemotherapy and radiotherapy in patients with rectal cancer, but not the overall survival rate." (PMID 36230725, 2022). "The 20–30% of locally advanced rectal cancer patients undergoing preoperative concurrent chemoradiotherapy had no expected efficacy, and ERCC1 overexpression was found in these tumor tissue patients." (PMID 36230725, 2022).